AFP (alpha fetoprotein)
Diseases named in the same sentence as AFP in open-access papers (continued):
Sharing a sentence is not in itself a finding about the gene and the disease.
tumor (continued). "Serum tumor markers, primarily AFP, CA-125, and hCG can be monitored every 1–3 months in the first year and every 3–6 months after that." (PMID 39734342, 2024). "Univariate analysis revealed that pre-treatment albumin and INR along with well-characterized risk factors, including tumor burden (Milan criteria, index lesion size, and BCLC staging), AFP levels, and response to LDT, were all associated with TTP." (PMID 38201639, 2024). "In summary, our results elucidate the mechanism by which AFP contributes to tumor growth by modulating the HSP90-client complex." (PMID 39135041, 2024). "AFP level and tumor size have been used in many HCC prognoses models and have been proven to have good predictive ability and evaluation effects." (PMID 37067674, 2024). "In our patient reported herein, we repeated the imaging during the atezo/bev therapy when the serum AFP level began to increase gradually, and found that fortunately, the tumor had not only shrunk in size, but was also resectable." (PMID 38071671, 2024). "Monitoring AFP levels is a valuable tool for diagnosis, evaluating treatment response, and detecting tumor recurrence." (PMID 39791094, 2024). "The novel feature in our case was the marked rise in serum AFP during pre-operative chemotherapy, despite a substantial reduction in tumor size, both clinically and radiologically." (PMID 38098239, 2024). "Results from the TCGA cohort indicated that patients in the high-risk group presented with more advanced tumor stages, higher tumor grades, increased vascular invasion, and elevated AFP levels (p < 0.05)." (PMID 39132167, 2024). "Among those based on blood markers, alpha-fetoprotein (AFP) is widely studied as an HCC tumor marker, but its efficacy for early detection is debated, due to varying sensitivities and potential false positives." (PMID 39200802, 2024). "While limited to sample size, no further statistical correlation was reached between baseline AFP levels and clinicopathological features, including tumor burden, clinical responses, and prognosis." (PMID 38833154, 2024). "The scores of Model 2 ranged from 1 to 3 for tumor burden (sum of tumor size and number) and from 0 to 1 for AFP and ALBI grades." (PMID 38606106, 2024). "Following tumor marker evaluations, the levels of alpha-fetoprotein (AFP), carbohydrate antigen 19-9 (CA 19-9), and carcinoembryonic antigen (CEA) recovered to normal." (PMID 39109134, 2024). "The dual-marker panel had a higher sensitivity of 78.26% for stage I HCC than alpha-fetoprotein (AFP) of 47.83%, and a high sensitivity of 70.27% for detecting a single tumour (size ≤3 cm)." (PMID 38154055, 2024). "Numerous studies have reported that dynamic alterations in AFP levels can effectively indicate the response to various anti-tumor treatments, including hepatectomy." (PMID 38903723, 2024). "Restoration of PARD3 expression significantly increased the risk of tumorigenesis in berberine-treated mice and increased the tumour multiplicity, tumour volume and serum AFP level." (PMID 38317186, 2024). "Classic serum tumor markers include AFP, β-HCG, anti-Miller tube hormone (AMH), CA125, and CA199, but most of which are interfered by pregnancy status." (PMID 39309737, 2024). "By integrating clinical characteristics (including age, sex, tumor grade, tumor stage, AFP, TB, Alb, platelet and PT), we adopted univariate and multivariate Cox regression analyses to assess the independence of the model." (PMID 38531953, 2024). "Subgroup analysis on tumor number, maximum tumor diameter, presence of portal vein thrombosis, AFP level, and Child-Pugh class were conducted." (PMID 39411718, 2024). "For example, a pilot study involving patients with advanced HCC demonstrated that DFO treatment reduced serum alpha-fetoprotein (AFP) levels, a marker of tumor activity, suggesting potential anti-tumor effects." (PMID 39766056, 2024).
tumor (continued). "The tumor markers were as follows: AFP 1.60ng/ml, CEA 0.92 ng/ml, CA199 6.67U/mL, CA125 11.9U/mL, HE4 27.32pmol/L." (PMID 39026973, 2024). "The post-transplant tumor marker levels were 3 ng/mL, 13 U/mL, and 1.8 ng/mL for AFP, CA19-9, and CEA, respectively." (PMID 38473290, 2024). "The MTT assay and in vitro colony formation assay results recealed a significant suppression of proliferation in both AFP-producing tumor cell lines upon AFP knockdown." (PMID 39135041, 2024). "Serum AFP is a commonly used tumor marker for HCC diagnosis and holds a certain reference value, but it exhibits poor sensitivity and specificity for detecting HCC." (PMID 39310811, 2024). "As expected, following tumor resection, the AFP level fell rapidly to normal once the source of production had been removed." (PMID 38098239, 2024). "From the perspective of clinical factors, the greater the AFP value is, the larger the tumour, and the greater the possibility of MVI." (PMID 38281008, 2024). "Seven factors (i.e., Age, Gender, AFP, Tumor number, Tumor size, BCLC stages, and MVI) were identified as statistically significant factors associated with overall survival (OS) in HCC patients." (PMID 38904028, 2024). "Tumor shape, vascular morphology, LR-M category, necrosis and AFP level were different between the MVI-positive group and MVI-negative group (p < 0.05)." (PMID 39546065, 2024). "As a result, the potential benefits of combining AFP response with radiological tumor response in the salvage hepatectomy population merit further investigation." (PMID 38433845, 2024). "In terms of OS, tumor size (OR = 2.39, 95% CI: 1.38–4.16, P = 0.002), AFP (OR = 2.80, 95% CI: 1.64–4.77, P < 0.001), and GPR (OR = 1.87, 95% CI: 1.07–3.26, P = 0.029) were identified as significant predictors." (PMID 38773511, 2024). "Intracellularly, AFP participates in autophagy, apoptosis signaling, and tumor growth through processes like PI3K/Akt/mTOR pathway activation, Fas mRNA translation, and RAR nuclear translocation." (PMID 39135041, 2024). "The median PFS was notably longer in tumor biomarker response groups (high AFP cohort: 13.7 vs 6.2 months, hazard ratio [HR] 0.36, 95% CI 0.20-0.62, p<0.001; high DCP cohort: 15.6 vs 9.3 months, HR 0.44, 95% CI 0.26-0.74, p=0.002)." (PMID 39726604, 2024). "The model features staged AFP cut-offs based on tumour size and considers the number of active nodules." (PMID 39519230, 2024). "The RETREAT score, integrating explant tumour burden (diameter of largest viable tumour + number of tumours on explant pathology), presence of microvascular invasion and AFP level at transplantation, allows for the accurate prediction of HCC recurrence." (PMID 38304238, 2024). "The AUCs of the MODEL 2 by combining CA50, CA19‐9, and AFP were higher than those of the single serum tumor markers." (PMID 38924330, 2024). "The RETREAT Score awards points based on AFP at time of transplant, presence of microvascular invasion on explant pathology, and explant tumor burden, and its accuracy and simplicity has resulted in wide adoption." (PMID 39085572, 2024). "We confirmed the findings on tumor burden by measurement of AFP, which was significantly decreased in co-housed HFD offspring compared to their separately housed offspring (median AFP 0.7 vs. 223 ng/ml, p <0.001)." (PMID 38681863, 2024). "PIVKA-II reflects tumor-induced alterations in vitamin K metabolism and is particularly useful in cases where AFP levels remain within the normal range." (PMID 39839797, 2024). "BDCA2+ pDCs in tumor tissue were associated with high alpha-fetoprotein (AFP) levels, advanced tumor-node-metastasis staging, and increased tumor infiltration by Tregs and IL-17-producing cells." (PMID 39146202, 2024). "Regular follow-up with imaging and tumor marker assessments of alpha-fetoprotein (AFP), human chorionic gonadotropin (HCG), and lactate dehydrogenase (LDH) are crucial for early detection of recurrence and management of long-term treatment sequelae." (PMID 39171067, 2024).
tumor (continued). "Although serum AFP has been widely utilized as a tumor marker for HCC diagnosis and screening, its sensitivity and specificity are not sufficiently high, necessitating further improvements." (PMID 38383334, 2024). "Further examination indicated that lower FCN3 expression was significantly correlated with higher alpha-fetoprotein (AFP) level, larger tumor size, higher TNM stage, and earlier recurrence." (PMID 38698462, 2024). "SNP rs2640908 was found to be predominant among late-stage HCC patients, especially those who were elderly, with large tumor size, increased serum α-fetoprotein (AFP) levels, and advanced tumor node metastasis (TNM) stage." (PMID 39335475, 2024). "Among the 23 radiological and clinical features, size, arterial peritumoral enhancement (APE), tumour margin and alpha-fetoprotein (AFP) were independent influencing factors for MVI in HCC." (PMID 38281008, 2024). "AFP, as a tumor biomarker, directly modulates tumor cell behavior and the TME by interacting with tumor-associated cells and molecules." (PMID 38660138, 2024). "Recently, the liquid biopsy has emerged as a potential tool for early HCC detection, with circulating tumor DNA, cells, and extracellular vesicles showing promise, compared to serum AFP levels." (PMID 39200802, 2024). "Serum tumor markers included alpha-fetoprotein (AFP) at 2018 ng/mL, CEA at 1.5 ng/mL, and CA19-9 at 22.8 u/mL." (PMID 39421875, 2024). "Patients with AFP > 20 ng/ml, age>50, tumor diameter>6 cm, early recurrence (+), and advanced BCLC stage exhibited LAPTM4B up-regulation (P < 0.05)." (PMID 38388484, 2024). "The 2022 version of the BCLC classification also underscores the importance of liver function and AFP level, as well as tumor burden, when considering treatment strategies for HCC patients." (PMID 38606106, 2024). "Children's Hepatic International Collaboration (CHIC) is renowned for developing the well-known PRETEXT risk stratification, utilizing factors such as the age of onset, tumor invasion extent, AFP level and metastatic status, etc.." (PMID 38390281, 2024). "The tumor achieved PR again and the alpha-fetoprotein level returned to normal after switching to the primary protocol for 3 months." (PMID 38728500, 2024). "The results showed that MVI, AFP, tumor burden, progression pattern and the multiplicative interaction terms of tumor load and mode of progression were statistically significant for the prognosis of patients (p< 0.001)." (PMID 38715786, 2024). "Model 1 was formulated with the following equation: 1.1 × the largest tumor size + 1.6 × tumor number + 2.2 × AFP + 4.3 × ALBI grade (1 and 2/3)." (PMID 38606106, 2024). "mALBI grade 1 or 2a, tumor size < 30 mm, AFP level < 400 ng/mL, and Atez/Bev TACE sequential therapy were selected as variables via univariate analysis." (PMID 39451736, 2024). "Tumour markers (beta human chorionic gonadotropin (hCG), alpha-fetoprotein (AFP), lactate dehydrogenase (LDH)) were within normal limits." (PMID 39011191, 2024). "All these findings allow us to assess that a high basal AFP level correlates with more aggressive tumor behavior." (PMID 38792876, 2024). "Laboratory investigations revealed markedly elevated tumor markers, with alpha-fetoprotein (AFP) at 2800 ng/mL and carbohydrate antigen 19-9 (CA 19-9) at 3800 U/mL, while carcinoembryonic antigen (CEA) levels were within normal limits." (PMID 39835045, 2024). "There were significant differences between the MVI-positive and MVI-negative groups in terms of tumor size (6.72 ± 3.12 cm vs. 4.29 ± 2.18 cm, p<0.001) and AFP level >400 ng/mL (p=0.046)." (PMID 39759152, 2024). "engineered AFP-CAR-T cells capable of selectively binding to the AFP158-166 peptide presented by HLA-A02:01 on the surface of tumor cells in vivo." (PMID 39569202, 2024).
tumor (continued). "Subsequent research indicated that HCC tumor-derived AFP (tAFP) synergizes with low-molecular-weight (LMW) molecules in impairing DC differentiation and function, with LMW molecules being necessary for tAFP to reduce the expression of DC maturation markers." (PMID 39334927, 2024). "A highly significant positive correlation was found between pre-op AFP and cumulative tumor size (p = 0.001)." (PMID 39749089, 2024). "AFP has various biological functions that not only acts as a tumor marker but also regulates cell proliferation, differentiation, and tumor formation." (PMID 38408930, 2024). "Of the 24 patients who achieved CR, 18 had all three tumor markers (AFP, DCP, AFP-L3) within the normal range." (PMID 39451767, 2024). "Our study is the first to explore the relationship between early AFP response and early tumor progression based on real-world data." (PMID 39767676, 2024). "This study also observed a similar result, which among the 97 HCC cases with BCLC stage A included in this study, the age, tumor size and AFP expression of patients were significantly correlated with the expression of CK19." (PMID 38332165, 2024). "Laboratory examination of the serum tumor marker levels revealed a serum alpha fetoprotein (AFP) level of 16.8 ng/mL (normal range < 10 ng/mL) and serum des-gamma-carboxyprothrombin (DCP) level of 326 mAU/mL (normal range < 40 mAU/mL), respectively." (PMID 38071671, 2024). "The 16-biomarker panels were divided into three categories of inflammatory markers (SAA, CRP, NLR, PLR, and LDH), TH1/TH2 cytokines (IL-2, IL-4, IL-5, IL-6, IL-8, IL-10, IFNγ, TNF, and GM-CSF), and HCC tumor markers (AFP and PIVKA-II)." (PMID 38409200, 2024). "Subsequent laboratory analysis indicated that the patient tested positive for HBV, and the tumor marker alpha-fetoprotein (AFP) was significantly elevated at 1210 ng/ml." (PMID 39267823, 2024). "The only validated non-invasive prognostic markers for HCC are tumor staging and AFP levels, and both have significant limitations in approximating tumor biology." (PMID 38660298, 2024). "If possible, tumor markers [i.e., alpha-fetoprotein (AFP) and β-human chorionic gonadotropin (β-HCG)] should be detected in both the serum and cerebrospinal fluid." (PMID 38665953, 2024). "These technologies can specifically inhibit the synthesis of AFP or prevent its interaction with target cells, thereby suppressing tumor growth and diffusion." (PMID 38660138, 2024). "EFNA1, a ligand of EphA2 receptor tyrosine kinase, is overexpressed in AFP‐producing HCC and can induce the expression of genes associated with tumor cell growth, angiogenesis, invasion, and metastasis, leading to poor prognosis in HCC patients with AFP." (PMID 39041652, 2024). "An elevation of serum AFP to 81 ng/mL was noted after the commencement of chemotherapy, and enlargement of the tumor and cystic component was observed on MRI." (PMID 38668041, 2024). "Thirdly, regarding the analysis of AFP, while it has shown promise as a potential predictor of early tumor progression, there are also limitations." (PMID 39767676, 2024). "AFP values ≥ 20 ng/mL significantly correlated with tumor size and higher histological grading; starting from AFP values ≥ 400 ng/mL, a significant correlation with Child–Pugh class B–C and female gender was also observed." (PMID 38792876, 2024). "In conclusion, serum AFP level, tumour size, tumour margin and APE are potential biomarkers for predicting MVI in HCC patients." (PMID 38281008, 2024). "Age, sex, marital status, T stage, N stage, surgery, chemotherapy, tumor size, AFP level, fibrosis score, bone metastasis, lung metastasis, and grade were independent prognostic factors for elderly patients with HCC." (PMID 37067674, 2024). "We developed a new prognostic model, called the TACE-prognostic (TP) score, based on tumor burden (sum of the largest tumor diameter and tumor number), alpha-fetoprotein, and Albumin-Bilirubin grade." (PMID 38606106, 2024).
tumor (continued). "Among all the tumor markers for HCC, alpha-fetoprotein (AFP) is the best-known tumor marker and has been used universally for decades." (PMID 39749089, 2024). "Some examples of tumors include the prostate-specific antigen (PSA), which indicates the health of the prostate, the alpha-fetoprotein (AFP), which indicates liver function, and the exosomes released by tumor cells, which disclose malignant activity." (PMID 39597170, 2024). "Elevated AFP, a crucial HCC tumor marker, correlates with ER and is positively associated with low differentiation, MVI, and tumor recurrence in HCC patients." (PMID 38463221, 2024). "Higher ECOG score, larger tumour size (>5 cm), heavier tumour burden (>50%), the existence of MVI or EHS and high AFP level (>400 ng/ml) were independent risk factors for patients’ OS." (PMID 39093862, 2024). "A progressive decline to normalization according to their half-lives (5–7 days for AFP and 1–3 days for bHCG) confirms that orchiectomy has removed all tumor disease, otherwise they provide early evidence of residual disease or recurrence." (PMID 38958901, 2024). "Subsequently, the relationship between these modules and various HCC risk factors, including tumor stage, histological grade, peritumoral inflammation, tumor vascular infiltration status, and alpha-fetoprotein levels were explored." (PMID 38255847, 2024). "For example, the MORAL (Model of Recurrence After Liver Transplantation) includes NLR, maximum pre-transplant AFP, largest pre-transplant tumor size, vascular invasion on explant, tumor grade on explant, and tumor size and number on explant." (PMID 39085572, 2024). "Spectral multiplexing approach has been previously successfully demonstrated in simultaneous detection of two different tumor markers, alpha fetoprotein (AFP) and carcinoembryonic antigen (CEA), by using multicolor QDs." (PMID 38584178, 2024). "In contrast, serum tumor markers such as AFP offer a non-invasive and reproducible approach for early diagnosis." (PMID 38799149, 2024). "The definitive diagnosis of HCC relies on imaging tests such as CT and MRI and tumor markers such as alpha-fetoprotein (AFP), while puncture pathology biopsy is the gold standard for diagnosis." (PMID 39376988, 2024). "The AFP level was closely correlated with the tumor’s progression, while cerebrospinal fluid LDH showed a slight increase." (PMID 39711964, 2024). "After adjusting for age, sex, ascites, tumor characteristics (size, number, distribution), and liver function parameters (ALB, AFP, AST, and TBIL), the association remained significant, with an adjusted HR of 5.96 (95% CI: 3.39–10.5; P < 0.001)." (PMID 39902133, 2024). "Despite a significant disparity in treatment response, AFP levels emerge as a promising non-invasive prognostic marker in this type of tumor, particularly in those who underwent curative-intent treatment." (PMID 38396674, 2024). "Before matching, the tumor characteristics, including number, single and total diameter, pretransplant AFP levels, and liver functions, were significantly different in the two groups." (PMID 39188937, 2024). "Pharmacological inhibition of PCSK9 enhanced tumor-specific killing and downregulated PD-1 expression of AFP-specific TCR-T." (PMID 39113701, 2024). "In their research conducted in 2023, Chen and Shi developed a continuous flow immunoassay system that utilised a piezoelectric quartz crystal biosensor to detect alpha-fetoprotein (AFP) as a marker for tumours." (PMID 39204840, 2024). "AFP is released into the amniotic fluid along with transudates from pathologically exposed fetal skin vessels and fetal tumor or placental tissues." (PMID 38256600, 2024). "Tumor markers were elevated, including alpha-fetoprotein (AFP: 289 U/mL), carbohydrate antigen 19-9 (CA 19-9: 109 U/mL), carcinoembryonic antigen (CEA: 1.4 ng/mL), and ferritin (519 ng/mL)." (PMID 39655079, 2024).